NUDT14 (nudix hydrolase 14)
Description:
Cytosolic pyrophosphatase hydrolyzing the diphosphate bond in various nucleotide-sugars with a higher efficiency for UDP-alpha-D-glucose and ADP-D-ribose.
Synonyms: UGPPase; UGPP
Tractability: Small molecule: a structure with a bound ligand is known; it has a high-quality binding pocket. PROTAC: its protein half-life has been measured.
Target class: Enzyme; Hydrolase
Gene: Protein-coding gene on chromosome 14 (105,172,937 to 105,181,323, reverse strand). Ensembl gene ENSG00000183828.
Subcellular location: Cytoplasm, cytosol
Subcellular location (Human Protein Atlas): Microtubules; Nucleoli
Pathways (Reactome):
Metabolism of proteins: Synthesis of dolichyl-phosphate-glucose
Gene Ontology:
Molecular function: ADP-glucose pyrophosphohydrolase activity; ADP-ribose diphosphatase activity; identical protein binding; protein binding; UDP-sugar diphosphatase activity; hydrolase activity, acting on acid anhydrides, in phosphorus-containing anhydrides; metal ion binding
Biological process: protein N-linked glycosylation; ribose phosphate metabolic process
Cellular component: cytosol
Genetic constraint (gnomAD): Loss-of-function variants: 22 observed, 19.48 expected, observed/expected ratio (o/e) 1.13, 90% interval 0.81 to 1.61. The upper end of that interval is the gene's LOEUF score, 1.61, which puts it in group 6 of 6, group 1 being the genes least tolerant of losing a copy. Missense variants: 251 observed, 264.43 expected, observed/expected ratio (o/e) 0.95, 90% interval 0.86 to 1.05. Synonymous variants: 109 observed, 110.65 expected, observed/expected ratio (o/e) 0.99, 90% interval 0.84 to 1.15.
Homologues: Orthologues: chimpanzee NUDT14 (99% identical), pig NUDT14 (86% identical), rat Nudt14 (84% identical), mouse Nudt14 (82% identical), guinea pig NUDT14 (81% identical), zebrafish nudt14 (55% identical), Drosophila melanogaster CG42813 (42% identical), Drosophila melanogaster CG42814 (36% identical), Caenorhabditis elegans C50F4.16 (31% identical). Paralogues in human: NUDT5 (21% identical).
Diseases named in the same sentence as NUDT14 in open-access papers:
NUDT14 is named in the same sentence as 2 diseases in open-access papers, as found by Europe PMC text mining. Sharing a sentence is not in itself a finding about the gene and the disease. The quoted sentences say what the papers report.
cancer (2 papers, 2017 to 2022). A tumor composed of atypical neoplastic, often pleomorphic cells that invade other tissues. "NUDT1, NUDT5, and NUDT14 are highly expressed in cancers, indicating a potential role of these NUDIX enzymes in cancer." (PMID 35168561, 2022). "NUDT1, NUDT5, and NUDT14 belong to the cluster of highly expressed NUDIX in cancer, pointing toward a potential role of these NUDIX enzymes in cancer, which has been previously proposed." (PMID 29142246, 2017). "However, a distinct cluster appeared when comparing cancer vs normal tissues, which contained NUDT1, NUDT5, NUDT8, NUDT14, and NUDT22, confirming a potential role of these NUDIX hydrolases in cancer." (PMID 29142246, 2017).
infection (1 paper, 2015). The state of being infected such as from the introduction of a foreign agent such as serum, vaccine, antigenic substance or organism. "Lower transcription levels of NUDT14, KLK10, SLC28A1, SMAD4 and SEPT7 during a series of stages of infection may reflect the inabilities of these genes to participate in glucose metabolism, tumorigenesis, nucleoside biosynthesis and transport, signaling and microtubule stabilization respectively." (PMID 25903558, 2015).